SNORA3C (small nucleolar RNA, H/ACA box 3C)
Gene: Small nucleolar RNA gene on chromosome 16 (2,796,408 to 2,796,532, reverse strand). Ensembl gene ENSG00000221719.
Gene Ontology:
Biological process: RNA processing
Cellular component: nucleolus
Homologues: Orthologues: mouse Gm24888 (79% identical), rat Snora3B (79% identical). Paralogues in human: SNORA3B (90% identical), SNORA3A (62% identical).